DDX17 (DEAD-box helicase 17)
Diseases named in the same sentence as DDX17 in open-access papers (continued):
Sharing a sentence is not in itself a finding about the gene and the disease.
colorectal cancer (8 papers, 1989 to 2025). A primary or metastatic malignant neoplasm that affects the colon or rectum. "In colorectal cancer, DDX17 is highly expressed and associated with poor prognosis." (PMID 41322492, 2025). "RNA sequencing analysis has revealed that DDX17 negatively regulates miR-149-3p expression, which suppresses the migration and invasion of colorectal cancer cells." (PMID 41322492, 2025). "We also interrogated the expression of DDX17 mRNA in a series of colorectal cancer cell lines from the CCLE dataset." (PMID 36593242, 2023). "Recent studies have shown that DDX17 participates in the pathogenesis and progression of various tumors, such as colorectal cancer, liver cancer, pancreatic ductal adenocarcinoma, and lung adenocarcinoma, and is also related to these tumors’ survival and prognosis." (PMID 40526173, 2025). "Since DDX5 and DDX17 are known mediators of Wnt signaling in colorectal cancer and DDX3 and DDX5 have been found to interact, we evaluated whether RK-33 treatment also influences DDX5 and DDX17 protein levels." (PMID 26311743, 2015). "The proteins DDX17, MPG and PAK1 have been linked to colorectal cancer." (PMID 22087225, 2011). "However, the functional role and mechanisms of DDX17 in colorectal cancer (CRC) malignant progression and metastasis remain unclear." (PMID 36593242, 2023). "A study demonstrated that DDX17 promotes epithelial-mesenchymal transition and metastasis via the miR-149-3p/CYBRD1 pathway in colorectal cancer (CRC) patients, which significantly contributes to aggressive progression and prognosis of CRC." (PMID 40526173, 2025). "DDX17 reduces the 3’-UTR binding of miR-149-3p to CYBRD1 by down-regulating miR-149-3p, which in turn increases CYBRD1 expression and intracellular iron levels, and ultimately promotes EMT process and metastasis of colorectal cancer cells." (PMID 41322492, 2025). "In contrast, in colorectal cancer (CRC), DDX17 levels exhibited a negative correlation with EMT, which is implicated in tumor invasion, migration, and metastasis, as well as DNA repair." (PMID 40526173, 2025).
glioma (8 papers, 2021 to 2025). A benign or malignant brain and spinal cord tumor that arises from glial cells (astrocytes, oligodendrocytes, ependymal cells). "In glioma, DDX17 expression was positively associated with stemness and negatively correlated with DNA repair and cell cycle regulation." (PMID 40526173, 2025). "It is reported that upregulation of DDX17 is associated with the progression and poor prognosis in glioma, in addition to an enhancement of the gefitinib resistance via activation of β-catenin." (PMID 37239217, 2023). "Consistent with our results, a recent research discovered that DDX17 was increased in glioma tissues and associated with worse clinical outcome of glioma patients." (PMID 36593242, 2023). "In gliomas, DDX17 expression is significantly elevated, which inhibits the expression of autophagy-associated protein Beclin1 by enhancing the biosynthesis of miR-34-5p and miR-5195- 3p, thus promoting the processes of malignant migration, invasion, and apoptosis of glioma cells." (PMID 41322492, 2025). "In neurological diseases, DDX17 is involved in the pathology of amyotrophic lateral sclerosis, an ophthalmoplegic subphenotype of myasthenia gravis and glioma." (PMID 37239217, 2023). "Furthermore, DDX17 has been shown to play a regulatory role in tumor progression across diverse cell types including breast cancer, non-small cell lung cancer, and glioma." (PMID 40526173, 2025). "The aberrant expression of DDX17 is closely related to the clinicopathological features of glial tumors, providing important clues for an in-depth understanding of the pathogenesis of gliomas and the development of new therapeutic strategies." (PMID 41322492, 2025). "Several studies have demonstrated the importance of DDX17 in glioma development." (PMID 41322492, 2025). "In A172 cells and T98G cells (glioma cell lines), DDX17 controls the biosynthesis of miR-34-5p and miR-5195-3p, respectively; both of these miRNAs target Beclin1 to inhibit autophagy and promote the migration and invasion of glioma cells." (PMID 35992805, 2022). "In glioma, DDX17 promotes glioma cell invasion by inhibiting autophagy." (PMID 35992805, 2022). "In addition, analysis of enhancer RNA (eRNA)-regulated immune-related genes (IRGs) indicates that DDX17 is one of the key genes regulated by eRNAs, which may affect glioma development by influencing the infiltration pattern of immune cells and altering the tumor microenvironment." (PMID 41322492, 2025). "For example, DDX5/DDX17 expression significantly correlates with the WHO grade and histological type of glioma patients." (PMID 35992805, 2022). "Some studies have reported that CELF1, DDX17 and ZNF326 are overexpressed in glioma." (PMID 34482818, 2021).
lung carcinoma (7 papers, 2017 to 2025). "MYL9 is the gene encoding myosin light chain 9, which is regulated by DDX17 in lung cancer and mediates the regulation of actin cytoskeletal rearrangement and cellular adhesion." (PMID 41322492, 2025). "DDX17 accelerates lung cancer progression by promoting reduced apoptosis." (PMID 38802460, 2024). "Further studies are warranted to explore whether DDX17 can regulate the survival of lung cancer cells by regulating the expression of these genes." (PMID 36164607, 2022). "DDX17 can bind the mRNAs of MYL9 and MAGEA6 to promote the expression of MYL9 and MAGEA6, regulate the process of cytoskeletal reorganization and autophagy in lung cancer cells, thus promoting the proliferation, migration, invasion and tumor growth of lung adenocarcinoma cells." (PMID 41322492, 2025). "We identified seven proteins (Amph, Dok3, Ddx17, Mbip, Rim2, Skap2, TACC3, and Usp33) that are predicted to be EGFR interaction partners and/or share interaction partners within the EGFR pathway, and three of these (Amph, Rim2, and TACC3) show increased expression levels in lung cancer." (PMID 27956147, 2017).
liver cancer (6 papers, 2025). An epithelial or non-epithelial malignant neoplasm that arises from the liver. "Aldolase A (ALDOA) K230/K322la weakens the binding to DEAD-box helicase 17 in liver cancer stem cells, and Ikzf1 K164la significantly decreases the binding to TH17 differentiation-related gene promoters." (PMID 40994548, 2025). "Circular RNA circDDX17 produced by reverse splicing of exons 2–5 of the DDX17 gene is down-regulated in HCCs and liver cancer tissues." (PMID 41322492, 2025). "This research suggests that DDX17 has a critical role in the maintenance of stemness in liver cancer stem cells, and its function is regulated by ALDOA lactylation." (PMID 41322492, 2025). "Since DDX17 is a significant transcription factor in liver cancer, we speculated whether DDX17 can regulate TFPI2 expression." (PMID 40765823, 2025). "Utilizing the CPTAC database, we further examined DDX17 protein expression levels and found upregulation in Breast, Colon, Ovarian, Clear cell RCC, UCEC, Lung, PAAD, Head and neck, Glioblastoma, and Liver cancers compared to adjacent normal tissues (p < 0.05)." (PMID 40526173, 2025).
prostate carcinoma (6 papers, 2013 to 2025). A carcinoma that arises from epithelial cells of the prostate gland. "DDX17 is highly expressed in prostate cancer tissues and is essential for the proliferation and migration of prostate cancer cells." (PMID 36593242, 2023). "SNHG20, as a competing endogenous RNA, upregulates DDX17 expression to promote the development of prostate cancer." (PMID 35992805, 2022). "Studies have shown that there is an increase in DDX5 and DDX17 expression levels in breast, cervix, colon, and prostate cancer." (PMID 35237661, 2022). "To study the genome-wide contribution of Ddx5 and Ddx17 to the androgen-signaling pathway, we applied the same experimental strategy using the human LNCaP prostate cancer cell line that was treated with DHT for 24 h." (PMID 24275493, 2014).
lung adenocarcinoma (5 papers, 2020 to 2025). A carcinoma that arises from the lung and is characterized by the presence of malignant glandular epithelial cells. "Studies have shown that DDX17 regulates autophagy and actincytoskeleton remodeling in lung adenocarcinoma through MAGEA6 andMYL9 signaling." (PMID 38802460, 2024). "Based on the possible role of DDX17 on gene expression regulation reported previously in the literatures, we have performed high throughput transcriptomic sequencing by using lung adenocarcinoma H1299 LUAD cells with stable DDX17 knockdown." (PMID 36273228, 2022). "A higher expression of DDX17 protein was also detected in lung adenocarcinoma tissues using UALCAN cancer database, and the expression level of DDX17 was correlated with tumor stage and grade at varying degrees." (PMID 36273228, 2022). "Here, we demonstrated that DDX17 promoted the proliferation, migration and invasion of H1299 and A549 lung adenocarcinoma cells." (PMID 36273228, 2022). "Two candidate genes, namely MYL9 and MAGEA6 were selected for further studies as the potential effectors of DDX17 protein, mediating respectively its functions in cytoskeleton remodeling and autophagy of lung adenocarcinoma cells." (PMID 36273228, 2022). "Upon searching published papers and the LncMap database, we identified that five TFs—DDX17, STAT1, PPARG, ETS1, and E2F6—were closely associated with adenocarcinoma of the lung and HCG23." (PMID 32322582, 2020). "Additionally, DDX17 modulates the expression and alternative splicing of genes involved in apoptosis and proliferation in lung adenocarcinoma cells." (PMID 40526173, 2025). "Based on these reports, we investigated whether DDX17 regulates autophagy process in lung adenocarcinoma cells." (PMID 36273228, 2022). "However, the role of DDX17 in lung adenocarcinoma (LUAD) remains unclear." (PMID 36164607, 2022). "However, the biological role of DDX17 in the pathogenesis of lung adenocarcinoma (LUAD) has not been well characterized." (PMID 36273228, 2022).
non-small cell lung carcinoma (4 papers, 2020 to 2025). A group of at least three distinct histological types of lung cancer, including non-small cell squamous cell carcinoma, adenocarcinoma, and large cell carcinoma. "Upregulated DDX17 expression has been reported to be associated with resistance to the tyrosine kinase inhibitor drug, gefitinib in non-small cell lung cancer (NSCLC) cells." (PMID 33178205, 2020). "Our previous study demonstrated that DDX17 contributed to gefitinib resistance by promoting nuclear translocation and activation of β-catenin in non-small cell lung cancer." (PMID 36593242, 2023). "In non-small cell lung cancer (NSCLC), DDX17 showed significant positive correlations with angiogenesis, stemness, metastasis potential, and inflammatory responses, while it negatively correlated with the cell cycle." (PMID 40526173, 2025).
ovarian carcinoma (3 papers, 2023 to 2025). A malignant neoplasm originating from the surface ovarian epithelium. "This suggests that DDX17 promotes the proliferation, migration and invasion of ovarian cancer cells, providing a new potential target and theoretical basis for ovarian cancer research." (PMID 41322492, 2025). "The results suggest that the lncRNA FAM225B can increase PDIA4 expression by combining with DDX17, inhibiting the process of ovarian cancer." (PMID 37720188, 2023). "This research study supports the fact that lncRNA FAM225B in ovarian cancer can upregulate PDIA4 by directly binding to DDX17, inhibiting the activities of ovarian cancer cells." (PMID 37720188, 2023). "In conclusion, the main findings of our study indicate that lncRNA FAM225B plays an inhibitory role in ovarian cancer via the DDX17/PDIA4 axis." (PMID 37720188, 2023). "In this study, we demonstrated that lncRNA FAM225B elevates PDIA4 by directly binding to DDX17, restricting the biological function of ovarian cancer cells." (PMID 37720188, 2023). "The RT-qPCR and Western blot assays revealed that DDX17 was expressed at low levels in the serum of patients and cell lines of ovarian cancer (both P < 0.01)." (PMID 37720188, 2023). "Therefore, in ovarian cancer, lncRNA FAM225B promotes PDIA4 expression through DDX17, which in turn inhibits ovarian cancer progression." (PMID 39022688, 2024). "The GEPIA database showed that DDX17 was lowly expressed in ovarian cancer." (PMID 37720188, 2023). "Furthermore, to elucidate the molecular mechanism of action of lncRNA FAM225B in the development of ovarian cancer, we verified the direct interaction between lncRNA FAM225B and transcription factor DDX17 in ovarian cancer cells using RNA pull-down and RIP assays." (PMID 37720188, 2023). "In ovarian cancer cells, the binding of FAM225B to DDX17 upregulates the expression of PDIA4, which in turn inhibits the progression of ovarian cancer cells." (PMID 41322492, 2025). "RT-qPCR and Western blot assays were performed to detect the expression levels of the lncRNAs FAM225B, DDX17, and PDIA4 in the serum of patients with ovarian cancer and cell lines." (PMID 37720188, 2023). "DDX17 as a transcription factor, binds to the PDIA4 promoter to promote transcription, and restoration of PDIA1 expression inhibits the malignant phenotype of ovarian cancer cells." (PMID 39022688, 2024). "To determine whether PDIA4 participates in the molecular mechanism of lncRNA FAM225B in the development of ovarian cancer, we predicted that lncRNA FAM225B would inhibit PDIA4 expression by binding to the transcription factor DDX17." (PMID 37720188, 2023). "However, it is not apparent whether DDX17 regulates PDIA4 in ovarian cancer cells." (PMID 37720188, 2023).
amyotrophic lateral sclerosis (2 papers, 2022 to 2025). Amyotrophic lateral sclerosis (ALS) is a neurodegenerative disease characterized by progressive muscular paralysis reflecting degeneration of motor neurons in the primary motor cortex, corticospinal tracts, brainstem and spinal cord. "In amyotrophic lateral sclerosis (ALS), DDX17 upregulation helps repair DNA damage caused by FUS and inhibits FUS-induced neurotoxicity." (PMID 35992805, 2022). "In neurological diseases such as amyotrophic lateral sclerosis, the interaction between DDX17 and mutant FUS proteins is involved in neuronal protection." (PMID 41322492, 2025).
cervical carcinoma (2 papers, 2022). A carcinoma arising from either the exocervical squamous epithelium or the endocervical glandular epithelium. "Knockdown of both DDX5 and DDX17, in human cervical carcinoma cells suppressed cellular proliferation indicating their association with abnormal cell growth." (PMID 35237661, 2022). "The results showed that the expression of FSCN1 had a significant negative correlation (P < 0.05) with that of HLTF, HBP1, ZNF664, CTGF, DDX17, and KRT18 in cervical cancer tissues." (PMID 35178306, 2022). "Thus, FSCN1 negatively regulates four transcription factors (HLTF, HBP1, ZNF664, DDX17) and positively regulates ANGPTL4 (an angiogenic factor) and EPHA2 in both HeLa cells and cervical cancer tissues." (PMID 35178306, 2022).
COVID-19 (2 papers, 2022 to 2024). A disease caused by infection with severe acute respiratory syndrome coronavirus 2. "Our results showed that six spliceosomal component proteins (DDX5, DDX17, DDX39B, PRPF6, SNRNP40, and SNRNP200) were significantly down-regulated in COVID-19 patients." (PMID 35421082, 2022). "Interestingly, among these known virus-host PPIs, 13 splicing factors were downregulated in the COVID-19 patients, including three members of RNA helicase, DDX5, DDX17 and DDX1." (PMID 35421082, 2022).
emphysema (2 papers, 2024 to 2025). "The relative mRNA and protein expression levels of FOXO1and DDX17 were verified by RT-qPCR and Western Blot in emphysema mouse lung tissue." (PMID 38802460, 2024). "The results of RT-qPCR and Western Blot indicate that the mRNA and protein expression levels of FOXO1 and DDX17 in lung tissue of emphysema mice were significantly higher compared with those in air-exposed mice." (PMID 38802460, 2024). "Furthermore, in the lung tissues of the mouse emphysema model, the mRNA and protein expression levels of DDX17 are significantly elevated, suggesting that DDX17 may be involved in the pathogenesis of COPD, but the detailed roles and mechanisms are not clear." (PMID 41322492, 2025). "The results of RT-qPCR indicated that the mRNA expression level of FOXO1 in the lung tissue of emphysema mice was elevated compared with AIR group mice, and the mRNA expression level of DDX17 was also increased." (PMID 38802460, 2024). "Lastly, the verification of mRNA and protein expression levels in the lung tissue ofmouse emphysema model may only indicate that FOXO1 and DDX17 are related to regulatory genes of T-cell immune responses, but it does not mean that FOXO1 and DDX17 are direct regulatory genes of T-cell function." (PMID 38802460, 2024).
fatty liver disease (2 papers, 2024 to 2025). A reversible condition wherein large vacuoles of triglyceride fat accumulate in liver cells via the process of steatosis. "In addition, DDX17 is involved in the regulation of M1 macrophage activation and thus is associated with hepatic steatosis and fibrosis." (PMID 41322492, 2025). "In vivo studies have shown that hepatocyte‐specific knockout of DDX17 attenuates MCD‐ or HFD‐diet‐induced hepatic steatosis, inflammation and fibrosis." (PMID 38303609, 2024). "In our present study, hepatocyte‐specific knockout of DDX17 attenuated MCD or HFD‐diet‐induced hepatic steatosis, inflammation and fibrosis." (PMID 38303609, 2024). "Furthermore, hepatocyte‐specific DDX17 knockout significantly alleviated hepatic steatosis, inflammatory response and fibrosis in mice after the administration of MCD and HFD." (PMID 38303609, 2024). "Overall, our study reveals the role of the DDX17/Cyp2c29/ 14, 15‐EET pathway in lipid metabolism and subsequent inflammatory response and provides promising targets for the treatment of hepatic steatosis, inflammation and fibrosis." (PMID 38303609, 2024).
gastric cancer (2 papers, 2023 to 2025). A primary or metastatic malignant neoplasm involving the stomach. "Moreover, DDX17 was one of the hub genes associated with acquired resistance to cisplatin and fluorouracil combination-based chemotherapy in gastric cancer patients." (PMID 36593242, 2023). "DDX17 is up-regulated in gastric cancer cells with acquired resistance to the combination of cisplatin and fluorouracil chemotherapy, and is identified as a pivotal gene in the protein-protein interaction network, which is closely related to the overall survival of patients." (PMID 41322492, 2025). "The poor overall survival of gastric cancer patients with high expression of DDX17 suggests that DDX17 may play an important role in the mechanism of drug resistance in gastric cancer." (PMID 41322492, 2025). "Therefore, DDX17 may be a potential target for the treatment of gastric cancer and overcoming chemotherapy resistance." (PMID 41322492, 2025).